INS (insulin)
Diseases named in the same sentence as INS in open-access papers (continued):
Sharing a sentence is not in itself a finding about the gene and the disease.
Hypoglycemia (continued). "In contrast to the impaired glucose-stimulated insulin secretion, amino acids trigger insulin release in some individuals with KATPHI, causing severe protein-induced hypoglycemia." (PMID 23384201, 2013). "This study examines the likelihood and evolution of overall and hypoglycemia-inducing variability of insulin sensitivity in ICU patients based on diagnosis and day of stay." (PMID 23437328, 2013). "The items related to fear of hypoglycemia, weight gain and complications of insulin which appear to be important in other studies were not consistently weighted in the exploratory factor analysis of this study population." (PMID 24236071, 2013). "Insulin inhibits gluconeogenesis and glycogenolysis and stimulates uptake of glucose in muscles and adipocytes, leading to hypoglycaemia." (PMID 24616771, 2013). "On the other hand, the ORIGIN trial demonstrates the cardiovascular safety of insulin therapy, provided that the incidence of hypoglycemia remains reasonable." (PMID 24348585, 2013). "We also report sex- and age-specific changes in glucose homeostasis, including fasting hypoglycemia, and increases in glucose tolerance, insulin sensitivity and glucose uptake that are most prominent in male animals." (PMID 24023810, 2013). "The current use of intensive insulin treatment is inadequate, as it leads to a marked increase in episodes of severe hypoglycemia." (PMID 26824930, 2013). "We attenuated the β-cell ER proinsulin synthesis with a treat-to-target insulin therapy while avoiding hypoglycemia and weight gain." (PMID 23408938, 2013). "In total, 4% (n = 11) of patients gave actively dangerous responses to hypoglycaemia, such as increasing dosages (including OHAs and insulin), or going to sleep." (PMID 23451219, 2013). "If the subject achieved two consecutive days at goal, length of time needed to achieve target, total daily insulin doses, daily basal insulin doses, blood glucose fluctuations, and hypoglycemia episodes were calculated." (PMID 23737776, 2013). "Animal models of hyperinsulinemia are more complex with at least one report of accelerated fetal lung maturation in pregnant rabbits by a two-day intravenous (IV) infusion of insulin, but with significant hypoglycemia." (PMID 24204385, 2013). "Type-1-diabetes (T1DM) patients treated with unmodified regular human insulin (RHI) rarely achieve their glycemic target and often suffer from postprandial hyperglycemic incidents, together with an increased risk of hypoglycemia in the post-absorptive period." (PMID 24079842, 2013). "In our study plasma NEFA concentrations were suppressed with a mean value of 0.28 mmol/liter (range 0.05 to 1.42 mmol/liter), due to the dominant anabolic effects of insulin inhibiting the lipolytic response to hypoglycemia." (PMID 24228030, 2013). "The frequency of nocturnal, mild-to-moderate hypoglycemia was lower with ExBID (15%) than with insulin (29%)." (PMID 23256660, 2013). "Autonomous production of excessive amounts of insulin resulting in life-threatening hypoglycemia is the classical feature of the disease." (PMID 23738155, 2013). "Initial results showed that both insulin glargine/insulin glulisine regimens lowered blood glucose levels compared with premixed insulin, but with more individuals reaching target HbA1c and with less hypoglycaemia." (PMID 22998363, 2013). "Hypoglycaemic events per subject-year of exposure of 24-h and nocturnal hypoglycaemia were significantly lower with insulin detemir than with NPH insulin (rate ratio 0.76, 95% CI 0.60–0.97, P = 0.028 and 0.62, 95% CI 0.47–0.84, P = 0.002, respectively)." (PMID 23094597, 2013). "Hypoglycaemia stems from an excess of insulin action relative to endogenous and exogenous glucose supply." (PMID 23130654, 2013). "In patients with a history of (severe) hypoglycemia drugs such as SU, glinides and insulin should be avoided and less stringent blood glucose targets pursued." (PMID 23574917, 2013).
Hypoglycemia (continued). "A detectable insulin level is inappropriate at the time of hypoglycemia and is consistent with insulin excess." (PMID 23384201, 2013). "Metformin as added to insulin-based regimens has been shown to improve glycemic control, limit changes in body weight, reduce hypoglycemia incidence, and to reduce insulin requirements (sparing effect), allowing a 15–25% reduction in total insulin dosage." (PMID 23415113, 2013). "The presence of MCT-1 allows pyruvate, elevated during anaerobic exercise, to enter the beta cell and through the triggering pathway (KATP-mediated), increase insulin release resulting in hypoglycemia." (PMID 23384201, 2013). "Of note, secretagogues with the ability to prevent adverse effects (e.g., weight gain and hypoglycemia), to stimulate insulin biosynthesis, or to protect β cells from death are rare." (PMID 23573144, 2013). "We have developed a treat-to-target insulin therapy, aiming to reduce β-cell proinsulin sybnthesis while avoiding hypoglycemia." (PMID 23408938, 2013). "FynKO mice also had reduced glucose excursion during glucose tolerance tests along with fasting hypoglycaemia and low levels of plasma insulin." (PMID 24312371, 2013). "Clinically, those results indicate a decreasing likelihood of hypoglycemia induced by large rises (variations) in insulin sensitivity over short measurement and intervention intervals as days of ICU stay increase based on the one-sided threshold results." (PMID 23437328, 2013). "The patient continued to have insulin dependency, but also had multiple episodes of hypoglycemia during intravenous insulin infusion." (PMID 23350652, 2013). "The only study to reduce both mortality and hypoglycemia was notable in modulating both insulin and nutrition inputs to achieve good control with lesser insulin and thus reduce hypoglycemic risk." (PMID 23437328, 2013). "The pathophysiology of KATPHI is characterized by a failure to suppress insulin secretion as glucose concentration falls, manifesting as severe fasting hypoglycemia, and a failure to increase insulin secretion in response to a glucose load." (PMID 23384201, 2013). "Intensive insulin therapy was avoided in the current patients since it is related to high incidence of life-threatening hypoglycemia." (PMID 22829443, 2013). "There are mainly three ways to rescue for hypoglycemia: mathematically minimizing the SC accumulation, suspending the insulin delivery (termed as prediction/suspending solution), and using glucagon as a counterregulatory agent in closed-loop system." (PMID 24260042, 2013). "In view of patients' welfare, there is still an obvious need for development of antidiabetics that protect against hypoglycemia, enhance insulin synthesis, or improve β-cell protection." (PMID 23573144, 2013). "Our patient was very short (131.1cm, -4.9 standard deviation) at 14.3 years and showed profoundly impaired growth hormone responses to pharmacological stimulants: 0.15μg/L to insulin-induced hypoglycemia and 0.39μg/L to arginine." (PMID 24377430, 2013). "First, the proposed algorithms can coordinate the insulin and glucagon delivery simultaneously, such that more hypoglycemia can be minimized or avoided and more glucose concentrations can be kept within the normoglycemic range." (PMID 24260042, 2013). "If T2D patients were treated with insulin, the overall rate of hypoglycaemia was reported to be low and about one third that of patients with T1D; however, when considering advanced stages of T2D, the frequency approaches that of T1D." (PMID 24053606, 2013). "Long-acting (analog) insulins have a lower propensity to induce severe hypoglycemia compared to neutral protamine Hagedorn (NPH) insulin." (PMID 23574917, 2013). "Hypoglycemia occurs most commonly in diabetic patients with insulin treatment and rarely in normal subjects with prolonged fasting or in patients with hepatic failure or insulin-secreting tumors." (PMID 23520526, 2013).
Hypoglycemia (continued). "The importance of AVP along with CRH as physiological modulators of ACTH secretion in response to insulin-induced hypoglycemia has been demonstrated in humans." (PMID 23486926, 2013). "After insulin administration, the rats were video-monitored for 4-5 hours and hypoglycemia was confirmed through BG levels measured from the tail vein." (PMID 24386156, 2013). "VMH ROS production and S-nitrosylation were quantified following three consecutive daily episodes of insulin-hypoglycemia (RH model)." (PMID 23894333, 2013). "FynKO mice also display fasting hypoglycaemia despite decreased insulin levels, which suggested that hepatic glucose production was unable to compensate for the increased basal glucose utilization." (PMID 24312371, 2013). "In contrast, increased amounts of insulin present in the circulation will reduce or even prevent the mobilization of glucose which can result with hypoglycemia." (PMID 23935617, 2013). "Another strategy to avert hypoglycemia is a combination of glucose prediction and insulin infusion suspending." (PMID 24260042, 2013). "Other laboratory results that support the diagnosis include a low insulin and c-peptide level during hypoglycemia, low beta hydroxybutyrate, and hypokalemia." (PMID 24194988, 2013). "Insulin-induced hypoglycemia has been suggested to increase hypothalamic ROS levels and decrease anti-oxidant defenses in normal and diabetic rats." (PMID 23894333, 2013). "In contrast, blood glucose level did fall further in response to insulin-hypoglycemia in NAC-treated rats." (PMID 23894333, 2013). "As a pleiotropic hormone, insulin effects range from the well-known hypoglycemia to regulation of cell growth and differentiation." (PMID 24204385, 2013). "A pre-specified meta-analysis of hypoglycaemia across the three studies showed significantly less confirmed overall (17% less) and nocturnal (36% less) hypoglycaemia, and significantly fewer severe hypoglycaemic events (86% less) for insulin degludec." (PMID 23199058, 2013). "Accumulated evidence has shown that hypoglycemia is the most important barrier to the intensification of insulin therapy." (PMID 24223662, 2013). "Although her insulin and C-peptide levels were lower during hypoglycemia, they were still above the reference limits (61.9 μIU/mL and 1.97 pmol/L, resp)." (PMID 23738155, 2013). "Her total insulin requirements dropped to 10 units/day with frequent hypoglycaemia, with a significant proportion nocturnal; pre-conception requirements had been 25–30 units daily." (PMID 24616775, 2013). "That fear stems from the fear of hypoglycemia and of injections, but also from concerns about weight gain or from historical issues, such as relatives who started insulin treatment and fared badly." (PMID 23841986, 2013). "Consistent with the clinical diagnoses, the neonates with HH showed excessive and inappropriate insulin release during hypoglycemia." (PMID 24228030, 2013). "Insulin IP (15 U/kg), in rats fasted (14–16 hours), induced hypoglycemia, defined as <3.5 mM blood glucose (BG), in 68% of diabetic (STZ) and 86% of control rats (CON)." (PMID 24386156, 2013). "Traditionally, morning fasting hyperglycemia is attributed to activation of counter-regulatory mechanisms or a fall in insulin levels after an episode of nocturnal hypoglycemia, termed the Somogyi phenomenon." (PMID 22716962, 2012). "In the present study, no severe hypoglycemia events were reported in liraglutide-added group, while two patients in the insulin-increasing group reported severe hypoglycemia." (PMID 23153177, 2012). "Recently, the NIRTURE trial used a fixed dose of insulin on day 1and modulated glucose infusions versus standard care and found an increased rate of hypoglycemia in the treatment group." (PMID 22871230, 2012). "The Zip14 KO mice exhibited decreased circulating IL-6 with increased hepatic SOCS-3 following LPS, suggesting SOCS-3 inhibited insulin signaling which produced the hypoglycemia in this genotype." (PMID 23110240, 2012).
Hypoglycemia (continued). "The IAS is characterized by a combination of fasting hypoglycemia, high concentration of total serum immunoreactive insulin, and presence of autoantibodies to native human insulin in serum." (PMID 22567309, 2012). "The knockout mice also showed persistent hypoglycemia, hypoinsulinemia, enhanced glucose tolerance and elevated insulin sensitivity." (PMID 23077600, 2012). "Olfactory processing is modulated by the feeding state and insulin-induced hypoglycemia, and central insulin administration is well known to decrease food intake and body weight." (PMID 23251461, 2012). "It is well known that metformin leads to hypoglycemia due to decreased hepatic glucose output and increased glucose utilization by muscles and liver (which is insulin-mediated)." (PMID 22251748, 2012). "In general, hypoglycemia in diabetic patients occurs when an imbalance between insulin/hypoglycemic agent’s intake and body’s physiological need exists." (PMID 23497433, 2012). "Normally, low glucose levels trigger glucagon release from α-cells to abrogate the deleterious effects of insulin-induced acute hypoglycemia." (PMID 22969729, 2012). "Although definitions varied, the incidence of hypoglycemia was markedly greater among patients treated with intensive insulin protocols (30% vs. 14%; RR 3.10, 95% CI 1.54 to 6.23, P = 0.002)." (PMID 23082798, 2012). "Substitution of short-acting (regular) insulin with rapid-acting insulin (e.g. lispro or aspart) reduces frequency of daytime hypoglycemia." (PMID 23497433, 2012). "The highest rates of hypoglycemia were found among those participants treated with insulin only (Int 6.09/100 person yrs; Std 2.64/100 person yrs) while the lowest were among those prescribed oral agents only (Int 1.93/100 person yrs; Std 0.20/100 person yrs)." (PMID 22646230, 2012). "So for these patients admitted for BBT, doctors prescribed less basal insulin in case of hypoglycemia events." (PMID 22720003, 2012). "Any future RCTs of intensive insulin should therefore first carefully pilot their protocol to ensure that hypoglycemia can be minimized." (PMID 23082798, 2012). "The highest rates of hypoglycemia were seen with prescription of insulin, either alone or in combination with other medications." (PMID 22646230, 2012). "Insulin use was also predicting hypoglycaemia when used in combination with oral antidiabetic drugs (3.65; 2.92-4.58)." (PMID 23075070, 2012). "Nonetheless, this is the first report of which we are aware in which insulin was paradoxically used to prevent postprandial hypoglycemia." (PMID 22937294, 2012). "On the first day insulin alone, and on the second day, either insulin alone or an infusion of antagonist was started in the same rat, before the insulin-induced hypoglycemia." (PMID 22969729, 2012). "The reason for such designs is that even one episode of hypoglycemia sensitizes the endocrine and metabolic system so that you would expect that on the second day the rats would need a different amount of insulin." (PMID 22969729, 2012). "Predictive marker-guided insulin administration protocols able to achieve and maintain glycaemic targets with minimal side effects like hypoglycaemia." (PMID 22870170, 2012). "Forty years after the discovery of insulin—in 1963—an insulin pump delivering insulin and glucagon (to counteract hypoglycemia) was designed by Kadish." (PMID 24278682, 2012). "Hypoglycaemia, which requires emergency medical assistance, is commonplace in patients with longstanding insulin-treated type 1 and type 2 diabetes." (PMID 24764523, 2012). "Some studies found the incidence of hypoglycemia was significantly higher in infants receiving insulin therapy than in controls." (PMID 22871230, 2012). "There was a trend towards a lower incidence of severe hypoglycaemia during treatment with insulin lispro in comparison with human insulin (p = 0.087)." (PMID 22727048, 2012).
Hypoglycemia (continued). "It plays a critical role in glucose homeostasis and the prevention of hypoglycemia, primarily by promoting glycogenolysis and gluconeogenesis in the liver and attenuating inhibition of these processes by insulin." (PMID 23185367, 2012). "Despite this array of oral agents and advances in insulin delivery, pharmacological intervention often falls short of treatment goals with the price of unwanted side effects, namely weight gain and hypoglycemia." (PMID 21707956, 2012). "Although our patient was reported to have mild hypoglycemia in the morning of her presentation, which led her to omit her insulin dose, the hypoglycemia had improved by lunch time." (PMID 22394704, 2012). "Prolonged hypoglycaemia can lead to hyperactivity of the adrenal glands, with increased cortisol secretion, insulin activity antagonism and to effective inhibition of maternal glucose use." (PMID 22269111, 2012). "The UK Hypoglycaemia Study found similar incidence rates of hypoglycaemia in those recently started on insulin and those treated with sulfonylureas but reported increased rates (25%) in those with a longer duration of insulin treatment." (PMID 23075070, 2012). "Critical blood sampling during hypoglycemia indicated hyperinsulinism, suggesting that L-Asp induced hypoglycemia in the patient through inappropriate insulin secretion." (PMID 23211036, 2012). "Reductions in oral medication and insulin dose were made consecutively to avoid hypoglycaemia, and the reduction in insulin was statistically significant only in the low-carbohydrate group at 6 months." (PMID 22562179, 2012). "Inappropriate insulin secretion in response to a meal can lead to hypoglycaemia within a few hours of meal ingestion (postprandial HH)." (PMID 23032149, 2012). "At the study visit, 213 patients [21.8% (95% CI: 19.2–24.4%)] in the insulin glargine group and 241 [47.6% (95% CI: 43.3–52.2%)] in the NPH insulin groups had experienced hypoglycaemia (any category) in the previous month (p < 0.0001)." (PMID 22340448, 2012). "Multivariable adjusted predictors of hypoglycaemia were prior anamnestic hypoglycaemia (OR 4.05), microvascular disease such as retinopathy (OR 3.27), clinically relevant depression (OR 1.81) and, with respect to pharmacotherapy insulin use (OR 2.99)." (PMID 23075070, 2012). "During critical illnesses, the physiological responses induced by hypoglycemia, such as the inhibition of insulin release and increased release of glucagon, epinephrine, growth hormone, and cortisol, are frequently impaired." (PMID 23062226, 2012). "Particular attention is warranted in patients with prior episodes of hypoglycaemia, microvascular disease such as retinopathy and in patients receiving insulin." (PMID 23075070, 2012). "There was a trend towards a higher incidence of all types of hypoglycaemia with NPH insulin, which was most notable for symptomatic hypoglycaemia." (PMID 22340448, 2012). "This variability is especially reflected by the wide range of hypoglycemia (3 to 100%) among patients randomized to intensive insulin protocols." (PMID 23082798, 2012). "Continuous subcutaneous insulin infusion (CSII) with a rapid-acting insulin analog improves the glycemic control and reduces the rate of hypoglycemia compared with multiple daily insulin injection." (PMID 23497433, 2012). "We and others also showed that hypothalamic AMPK activation by neuroglucopenia or insulin-induced hypoglycemia is required for the counterregulatory responses." (PMID 22590531, 2012). "In contrast, in B6 mice with insulin-induced hypoglycemia followed by KA-induced SE, we observed significant cell loss, as evidenced by decreased cresyl violet and NeuN-immunostaining in three hippocampal subfields (dentate hilus, area CA3 and area CA1)." (PMID 22867059, 2012).